SPOP (speckle type BTB/POZ protein)
Diseases named in the same sentence as SPOP in open-access papers (continued):
Sharing a sentence is not in itself a finding about the gene and the disease.
cancer (continued). "In summary, the multifaceted role of SPOP in cancer biology presents both challenges and opportunities." (PMID 40521202, 2025). "DAXX is a substrate protein of SPOP that maintains the survival of cancer cells by downregulating the transcription of various tumor suppressors." (PMID 40642070, 2025). "The identification of diverse ubiquitin substrates has underscored the dual role of SPOP in tumorigenesis, thus posing challenges to cancer therapy and attracting significant attention." (PMID 40521202, 2025). "To further validate this immune correlation and elucidate the role of SPOP in cancer progression, we further assessed the correlation between SPOP expression level and CD4+ T cell as well as CD8+ T cell infiltration level by immunohistochemistry." (PMID 39074086, 2024). "Compared with normal liver cells, SPOP-M35L shows a stronger affinity to IRF2BP2 in cancer cells, leading to the upregulation of cell proliferation and migration." (PMID 38409107, 2024). "In conclusion, our study first provides a systematic investigation of SPOP in pan-cancer and revealed that SPOP expression levels decreased in types of cancer and related to overall survival." (PMID 39074086, 2024). "The result indicates that high expression of SPOP profiles with higher CD4/8+ T infiltrating cells were correlated with a better survival in cancer patients." (PMID 39074086, 2024). "Many studies have been reported SPOP play a significant role in driving tumorigenesis in a variety of cancers, including prostate, breast, endometrium, liver, and colon." (PMID 39074086, 2024). "Regarding the regulation of cancer cell necroptosis by SPOP, this study suggests that PIM2 and ERK2 kinase can fine-tune key molecules through phosphorylating T403, T412, and S413 of RIPK3." (PMID 39540935, 2024). "In some cases, para-cancer tissue mRNA information was insufficient in the TCGA database, so we further estimated the overall expression differences of SPOP between cancer and para-cancer tissues combined with the TCGA and GTEx databases." (PMID 39074086, 2024). "Cluster analysis identified a pro-cancer role for the ERS high-risk subgroup, which had lower mutation rates of key genes (SPOP and MUC16), multiple low-expressed immune-related molecules, and differential expression in macrophages (M1 and M2)." (PMID 38643190, 2024). "SPOP–DAXX bodies, PML vesicles, and FET fusion proteins formed via multivalent interactions affect various cancers regarding gene fusion and mutation." (PMID 39006762, 2024). "Having demonstrated that SPOP mutations exert distinct effects dependently on cancer types, we set out to explore HCC-related SPOP mutations." (PMID 38409107, 2024). "SPOP proteins regulate various cancer-related substrates and play a crucial role in mediating PD-L1 degradation." (PMID 39048965, 2024). "Mutations in SPOP are found primarily in the MATH domain, which accelerates cancer progression by promoting the accumulation of oncogenic substrates, leading to increased cell proliferation, migration, and invasion." (PMID 39540935, 2024). "The relationships between the relative SPOP mRNA expression profiles and different clinicopathological characters of pan-cancer patients were downloaded from the TCGA dataset and performed in R software." (PMID 39074086, 2024). "We obtained 74 dysregulated SRGs between normal and cancer tissues, among which six genes (RPS6KA6, ABI3, PTTG1, E2F1, CBX7, and SPOP) were associated with the OS of CC patients." (PMID 37768206, 2023). "Several SPOP substrates important in a cancer context have been previously identified, such as BRD proteins, DRAK1 and LATS1." (PMID 37622993, 2023). "For example, SPOP can inhibit the growth rate of cancer cells in lung cancer, colorectal cancer, prostate cancer, and so on." (PMID 37941785, 2023). "Speckle-type POZ protein (SPOP) is a substrate adaptor in the ubiquitin proteasome system, and plays important roles in cell-cycle control, development, and cancer pathogenesis." (PMID 36856266, 2023).
cancer (continued). "Lastly, we assessed the importance of SPOP for IRF1 degradation in non-cancer-derived cells, and across species." (PMID 37622993, 2023). "Given that BRAF activity is elevated in SPOP-mutated cancers, the efficacy of AZ304 in these cancers should be investigated." (PMID 36585710, 2022). "Consistently, SPOP knockdown caused accumulation of ASCT2 in both breast and lung cancer cell lines, respectively, and markedly extended ASCT2 protein half-life." (PMID 35641493, 2022). "SPOP plays key roles in cancer development by promoting ubiquitination and degradation of the substrate protein of specific signalling pathways." (PMID 36474188, 2022). "Given that BRAF activity is elevated in SPOP-mutated cancers, elucidation of the SPOP-BRAF regulatory axis in further studies will be helpful in designing therapeutic strategies for SPOP-mutated cancers." (PMID 36585710, 2022). "Similar to our cell experiment results, some studies also found that high expression of SPOP suppressed the malignant biological behaviour of cancer cells in vitro via ubiquitin-dependent proteolysis of the signalling pathway." (PMID 36474188, 2022). "SPOP promotes K63-and K48-linked ubiquitination of TWIST1, predominantly at K73, thereby suppressing cancer cell migration and invasion." (PMID 36115849, 2022). "Cancer-associated mutations of SPOP disrupted the SPOP/DAXX nuclear bodies, driving DAXX accumulation and cancer progression." (PMID 35406602, 2022). "In contrast to other cancer types, studies have shown that SPOP is highly expressed in clear-cell renal cell carcinomas (RCCs)." (PMID 36360288, 2022). "In this review, we summarize the current understanding of SPOP’s functions in cancer and discuss how to design a rational therapeutic target." (PMID 36360288, 2022). "This meta-analysis summarized the clinicopathological and prognosis significance of SPOP expression in cancer patients." (PMID 34838022, 2021). "It has been shown that SPOP suppress tumorigenesis in human cancers via regulation of cell growth, apoptosis, migration, invasion, and drug resistance by targeting different downstream substrates." (PMID 34680332, 2021). "As these important roles of SPOP in cancers, increasing evidence pay attention to the relationship between SPOP and tumors in recent years." (PMID 34838022, 2021). "In contrast, SPOP has been considered as an oncogene in kidney cancer or cancers under hypoxic conditions to promote AKT kinase activity by degrading the tumor suppressor PTEN." (PMID 34353330, 2021). "The functions of SPOP in cancer is predominantly dependent on the function of its substrate proteins and the related signaling pathways." (PMID 34838022, 2021). "We demonstrate that while 5-AzaC can effectively inhibit SPOP-mutant PCa cell growth, it further enhances the anti-cancer efficacy of DTX both in vitro and in mice." (PMID 34588438, 2021). "In view of the relationship between SPOP mutations and activation of PI3K pathway in cancers, we next detected the alteration of SPOP in RCC cells." (PMID 35082669, 2021). "Similar to the effect of the ubiquitination-resistant mutant of Geminin, expression of cancer-derived SPOP mutants also increased Cdt1 binding to MCM2, CDC6, and ORC2 but had no influence on Geminin binding to Cdt1." (PMID 34599168, 2021). "In the term of the correlation of SPOP expression with clinicopathological characteristics, SPOP expression was insignificant between cancer and adjacent tissue in total (RR 1.44, 95% CI 0.90–2.32, I2 = 95%, random effect model, 11 comparisons, 2490 cases)." (PMID 34838022, 2021). "Understanding the clinical and biological characters of SPOP will lay the foundation and provide a novel view to screen potential targets for precise cancer therapy." (PMID 34838022, 2021). "SPOP has the potential function to act as a novel and effective biomarker for cancer diagnosis and prognostic stratification." (PMID 34838022, 2021).
cancer (continued). "Several cancer-relevant proteins have been identified as the substrates of SPOP, such as androgen receptor (AR), SRC-3, TRIM24, and BRD4, and these proteins are aberrantly upregulated in SPOP-mutated PCa cells and patient tissues." (PMID 34599168, 2021). "Subgroup analysis showed that the SPOP expression of adjacent tissue was significantly higher than that in cancer tissues of prostate and liver." (PMID 34838022, 2021). "The differential expression of SPOP have the potential function to act as a novel and effective biomarker for cancer diagnosis and prognosis." (PMID 34838022, 2021). "EC is the sixth most commonly diagnosed cancer in women worldwide, and multiple studies have been conducted to explore the function of SPOP in the tumorigenesis of EC." (PMID 31901237, 2020). "In conclusion, SPOP plays a dual role in the development and progression of human cancer by targeting its various substrates." (PMID 31901237, 2020). "Because the SPOP protein has context-dependent functions in different cancer types, future studies should focus on designing tissue- or cell-specific cancer drugs." (PMID 31901237, 2020). "Together, our data show that cancer-derived SPOP mutants fail to interact with ILF3, thereby leading to ILF3 stabilization and subsequent SGOC gene activation." (PMID 31772275, 2020). "Collectively, these results suggest that SPOP inhibits the cancer stem‐like capacity of tumorsphere cells." (PMID 32160650, 2020). "Another cancer-LLPS link is the tumour suppressor SPOP which interacts with proto-oncogenic substrates and undergoes LLPS, leading to substrate ubiquitination and degradation." (PMID 32364240, 2020). "We show that these cancer-derived SPOP mutants fail to earmark ILF3 for poly-ubiquitination and subsequent degradation, thereby accumulating ILF3 to subsequently activate the SGOC pathway and metabolic reprogramming." (PMID 31772275, 2020). "Overall, further exploration is required to discover a rationale for designing therapeutic strategies using SPOP inhibitors or promoters for human cancer patients." (PMID 31901237, 2020). "To date, our meta-analysis is the first to investigate the relationship between low SPOP expression and clinical prognostic value in 9 studies with 928 cancer patients." (PMID 31577764, 2019). "The current meta-analysis was performed to obtain a comprehensive evaluation of the relationship between SPOP expression and prognosis of cancer patients." (PMID 31577764, 2019). "The subgroup analysis according to cancer type demonstrated that low expression of SPOP was related to poor OS in digestive system cancers (high/low: HR = 0.46; 95% CI: 0.27–0.78, P = .003)." (PMID 31577764, 2019). "The underlying mechanisms involved in the relationship between low SPOP expression and poor prognosis of cancer patients have been universally investigated." (PMID 31577764, 2019). "A heat map of their fold changes after SPOP knockdown showed that they are oppositely regulated by SPOP in DU145 and 769-P cell lines, which further suggests SPOP has different functions in two cancers." (PMID 30237511, 2019). "So it is important to further elucidate the underlying mechanism that determines SPOP selectivity, and carefully evaluate the effects of SPOP regulators in both cancers." (PMID 30237511, 2019). "Meanwhile, it will be necessary to determine SPOP’s real function in other cancers during the future studies, and our data will be helpful to clarify it." (PMID 30237511, 2019). "To further elucidate the different roles of SPOP in two cancers, we studied the global gene expression patterns with RNA-Seq." (PMID 30237511, 2019). "Along with SPOP-mutant cancers, FOXA1-mutant cancers have been associated with the highest levels of AR transcriptional activity." (PMID 29581876, 2018). "SPOP-mutant cancers generally lack genetic alterations in the PIK3 pathway but show a distinct pattern of genomic alterations, including losses of CHD1 at 5q21, 2q, and 6q." (PMID 29581876, 2018).
cancer (continued). "Recent studies have firmly established that SPOP is a substrate-specific adaptor that binds Cul3 and exerts cancer-promoting or cancer-suppressive effects depending on the specific substrate in various cancers." (PMID 30607139, 2018). "The conflictive effects of SPOP in different cells can be partially explained by the wide spectrum of substrates and SPOP differential expression in diverse cancer types." (PMID 30607139, 2018). "Further insights into the functional and mechanistic basis of KLHL20 and SPOP in cancer development can be obtained from studies with suitable animal models, especially genetically engineered mouse models." (PMID 27200299, 2016). "Immunohistochemistry and qPCR revealed that SPAST, STX18 and SPOP were expressed in the epithelium of benign and cancer areas of the high and the low inflammation cohorts." (PMID 26863016, 2016). "In particular, Keap1, KLHL20, and SPOP are the most reported Cul3 substrate adaptors for their impacts on various cancer types." (PMID 27200299, 2016). "Consistent with increased intrachromosomal rearrangements in SPOP mutant cancers, in vivo data nominated a functional role for SPOP in DSB repair, similar to BRCA1." (PMID 26374986, 2015). "We next selected MKN45 cells to study the effects of down-regulation of SPOP on cancer cell proliferation and migration." (PMID 25204354, 2014). "Conversely, context‐dependent oncogenic functions of SPOP have been observed in other cancer types." (PMID 41532714, 2026). "These domains enable SPOP to perform diverse roles across different cancer types." (PMID 40657370, 2025). "This brings SPOP into the limelight as a target to synergize cancer immune therapy." (PMID 39851497, 2025). "However, SPOP mutations led to enhanced LMNB2 degradation and disrupted NE integrity, causing nuclear rupture and making cancer cells more sensitive to farnesyltransferase inhibitor–based (FTI-based) therapies." (PMID 40662365, 2025). "Notably, the role of SPOP protein varies depending on the cancer context, highlighting the need for future studies to focus on developing cancer treatments that are specific to particular tissues or cell types." (PMID 40521202, 2025). "Thus, an accurate understanding of mechanisms for SPOP in cancer is critical for developing future effective drug development." (PMID 40521202, 2025). "Additionally, cancer-specific mutations within BRAF disrupt its interaction with SPOP, allowing BRAF to evade SPOP-mediated ubiquitination." (PMID 40521202, 2025). "The pathological role of SPOP in cancer is context dependent." (PMID 41148213, 2025). "The correlation matrix showed that SPOP expression was significantly positively associated with the recruitment of CD8+ T cells, CD4+ T cells, and Th1 cells, while negatively correlated with T cell recognition of cancer cells." (PMID 40657370, 2025). "We further evaluated the prognostic value of SPOP across different cancer types." (PMID 40657370, 2025). "However, the molecular heterogeneity of SPOP function across different cancers highlights the need for multi-omics analyses to establish consistent standards." (PMID 40657370, 2025). "The results revealed that normal and cancer samples expressed comparable SPOP." (PMID 38409107, 2024). "Thus, BCLAF1 enhances PD-L1 stability and expression through SPOP functional inactivation, resulting in cancer cells evading immune surveillance." (PMID 38340178, 2024). "Cancer development has been closely linked with phase-separated macromolecular condensates, including stress granules, DNA repair condensates, PRC1 condensates, super-enhancer condensates, SPOP/DAXX bodies and PML puncta." (PMID 39358623, 2024).
cancer (continued). "Thus, SPOP performs a unique role in regulating the homeostatic levels of PD-L1/PD-1 signaling in cancer cells, including prostate cancer, colorectal cancer, and esophageal adenocarcinoma." (PMID 38340178, 2024). "From this viewpoint, the ERKs and PIM2 signaling pathways, which play a key role in cell survival and cancer malignancy, may lead to cancer cell resistance to necroptosis by suppressing SPOP." (PMID 39540935, 2024). "Taken together, this study uncovers mutations in SPOP’s MATH lead to distinct functional consequences in context-dependent manners, rather than simply disrupting its interactions with substrates, raising a noteworthy concern that we should be prudent to select SPOP as therapeutic target for cancers." (PMID 38409107, 2024). "This correlation explains why low levels of SPOP protein are frequently observed in cancer cells." (PMID 39540935, 2024). "Thus, The TIMER, CIBERSORT, XCELL, QUANTISEQ, and EPIC algorithms were used to systematically investigate the relationship between TICs level and SPOP expression in 23 different types of cancer." (PMID 39074086, 2024). "In other words, the expression of SPOP has been observed a lower expression level in cancer tissues compared with normal tissues, besides a lower expression of SPOP significantly correlated with advanced grade of cancer." (PMID 39074086, 2024). "In addition, we tested the receiver operating characteristic (ROC) curves to evaluate how well SPOP as a biomarker is capable of discriminating between individuals in pan-cancer." (PMID 39074086, 2024). "As mammalian homologue of HIB, SPOP is involved in various human cancers." (PMID 37554435, 2023). "SPOP plays an essential role in various cellular processes via specific targeting of proteins for ubiquitination and subsequent proteasomal degradation during cancer development." (PMID 37036970, 2023). "In various cancer cell types and under differing expression conditions SPOP may play different roles and mechanisms." (PMID 37941785, 2023). "SPOP has been found to be differentially expressed in many cancers." (PMID 37622993, 2023). "Interestingly, 14-3-3γ has also been considered to play an important role in negatively regulating the programmed death ligand 1 (PD-L1) abundance by manipulating SPOP protein to influence immune response for cancer therapies." (PMID 35318320, 2022). "As most cancer-associated mutations in SPOP are missense and almost none are frameshift or nonsense, PALDRIC classifies it as an oncogene." (PMID 35975235, 2022). "Three cancer-associated SPOP mutants lacking the NLS sequence (ΔNLS-E47K, -S80R, and -W131G) accumulated exclusively in the cytoplasm in punctate patterns similar to those of SPOP-ΔNLS, but these mutants did not colocalize with BRAF." (PMID 36585710, 2022). "Immune checkpoint mediated by PD-1 and its ligand PD-L1 has been approved to be used for human cancer treatment, and it has been revealed that SPOP deletion could block the ubiquitin-induced PD-L1 degradation to increase PD-L1 protein expression." (PMID 35461336, 2022). "However, studies have shown that SPOP mutations in endometrial cancer promote the accelerated degradation and reduction of BRD4 protein, thus making cancer cells sensitive to BETis." (PMID 35402244, 2022). "Moreover, some cancer-associated BRAF mutants (T121I and S122Y) evaded SPOP-mediated regulation and were stronger activators of the MAPK/ERK cascade than wild-type BRAF." (PMID 36585710, 2022). "In addition, we found that mutations in degron-related regions bound by SPOP and RFWD2 are more likely to function as cancer drivers, consistent with previous findings that SPOP and RFWD2 regulate the degradation of critical oncogenes." (PMID 35836176, 2022). "Given that BRAF interacts with SPOP in an SBC motif-dependent manner, we further explored whether cancer-associated BRAF mutations that occur in the SBC motif would attenuate the SPOP-BRAF interaction and permit BRAF to evade SPOP-mediated ubiquitination." (PMID 36585710, 2022).